TRPC5 (transient receptor potential cation channel subfamily C member 5)
Diseases named in the same sentence as TRPC5 in open-access papers (continued):
Sharing a sentence is not in itself a finding about the gene and the disease.
Hypoglycemia (2 papers, 2024). A decreased concentration of glucose in the blood. "TRPC5-deficient animals exhibit striking parallels to PACAP-deficient mice in terms of recovery from insulin-induced hypoglycemia." (PMID 39375537, 2024). "Reduced hypoglycemia-evoked adrenalin secretion, as observed in Trpc5 KO deficient mice, contributes significantly to hypoglycemia-associated autonomic counter regulation." (PMID 39375537, 2024). "By comparing metabolites in the plasma, we identified reduced taurine levels after hypoglycemia induction as a commonality in TRPC5-deficient mice and HAAF patients." (PMID 39375537, 2024). "After having established the Trpc5–/– mouse phenotype, the authors show that supplementation of adrenaline or Englerin A (EA), an activator of TRPC4/TRPC5 channels, can mitigate the aggravated hypoglycemia conditions in TRPC5-deficient mice." (PMID 39487352, 2024). "Third, the hypoglycemia phenotype was pinpointed to the functional loss of TRPC5 channel activity specifically in chromaffin cells." (PMID 39375537, 2024). "Taken together, neither lower plasma concentrations of glucocorticoids or glucagon nor a reduced systemic response to these hormones are responsible for the phenotype of aggravated insulin-induced hypoglycemia in TRPC5-deficient mice." (PMID 39375537, 2024). "To verify the hypoglycemia phenotype in an independent TRPC5-deficient mouse model, we analyzed the Trpc5–/0_LB line (mixed 129EvSv/C57BL/6J background) which displayed significantly lower blood glucose levels and a lack of adrenaline elevation." (PMID 39375537, 2024). "Thus, TRPC5-deficient animals display not only more pronounced but also more prolonged hypoglycemia." (PMID 39375537, 2024). "Given this, and after having shown that TRPC5 is critical to the elevated adrenaline during insulin-induced hypoglycemia, the authors tested whether genetic loss of TRPC5 in RVLM neurons is critical to the autonomous counter regulation maintenance and found that is not." (PMID 39487352, 2024). "Our results show a striking parallel in sympatho-adrenal failure after the occurrence of hypoglycemia between Trpc5 KO mice and in HAAF patients." (PMID 39375537, 2024). "The release of systemic adrenaline in response to insulin-induced hypoglycemia is dependent upon TRPC5 channel activation in adrenal cells." (PMID 39375537, 2024). "We next evaluated a potential role of TRPC5 in catecholaminergic RVLM neurons in hypoglycemia counter-regulation." (PMID 39375537, 2024). "To investigate further the temporal profile of insulin-induced hypoglycemia of TRPC5 mutants and wild-type controls, we extended the observation period of the ITT from 60 to 150 min." (PMID 39375537, 2024). "Their work highlights a novel cell signaling pathway in which stimulation of PAC1 and muscarinic M1 receptors activate TRPC5 channels to induce sustained adrenaline secretion during the adrenergic counter-response to hypoglycemia." (PMID 39487352, 2024). "This study shows that TRPC5 channels have a crucial role in the adrenaline secretion required to prevent severe hypoglycemia." (PMID 39375537, 2024). "Collectively, these results assign TRPC5 channels a crucial role in adrenaline secretion and the stress response to hypoglycemia." (PMID 39375537, 2024). "In summary, the results show that TRPC5 channels play a central role in the regulation of hypoglycemia as well as in the reactive increase in plasma adrenaline concentration." (PMID 39375537, 2024). "The pivotal role of TRPC5 in hypoglycemia-evoked autonomic counter-regulation and adrenaline homeostasis was further supported by experiments with the TRPC5-specific agonist Englerin A (EA)." (PMID 39375537, 2024). "The comparative metabolome analysis of the plasma from TRPC5-deficient mice and HAAF patients during hypoglycemia pinpointed commonalities in the metabolic signature." (PMID 39375537, 2024). "Likewise, the TRPC5 blocker C31 efficiently blocked the hypoglycemia-evoked adrenaline elevation in vivo." (PMID 39375537, 2024).
Hypoglycemia (continued). "A new study implicates TRPC5 channels in adrenaline secretion during hypoglycemia." (PMID 39487352, 2024). "In summary, our organismal analyses together with our ex vivo studies provide striking parallels and converging lines of evidence that TRPC5 activity at the level of chromaffin cells constitutes a crucial step in the homeostatic counter-regulation of insulin-induced hypoglycemia." (PMID 39375537, 2024). "Taken together, pharmacological inhibition or genetic deletion of Trpc5 leads to a significant reduction in the hypoglycemia-evoked plasma adrenaline rise, corroborating the concept that TRPC5 channel activity controls the adrenaline-mediated counter-regulation in response to hypoglycemia." (PMID 39375537, 2024). "To test whether the lack of adrenaline rise in TRPC5-deficient animals causes the more severe insulin-induced hypoglycemia, we aimed to prevent aggravated hypoglycemia by supplementing adrenaline shortly after the insulin application in an adrenaline rescue experiment." (PMID 39375537, 2024). "Among the metabolites analyzed, we specifically observed the decrease in taurine levels as a coincidence between Trpc5 KO mice and HAAF patients under hypoglycemia." (PMID 39375537, 2024). "Taken together, these observations highlight a causal link between the absent adrenaline rise and the aggravated hypoglycemia and furthermore show that the catecholamine-evoked blood glucose rise itself is not impaired by Trpc5 deletion." (PMID 39375537, 2024). "Thus, aggravated insulin-induced hypoglycemia in Trpc5 KO animals is not paralleled by up- or downregulated secretion of corticosterone in the plasma." (PMID 39375537, 2024). "However, the defect in autonomic counter regulation in Trpc5 KO mice is not specifically triggered by induction of hypoglycemia but is also observed in other forms of stress and in HAAF patients, a reduced sympathetic activity is observed, which is upstream of the chromaffin cells." (PMID 39375537, 2024). "We show that insulin-evoked hypoglycemia is severely aggravated in mice lacking the cation channel proteins TRPC1, TRPC4, TRPC5, and TRPC6, which cannot be explained by alterations in glucagon or glucocorticoid action." (PMID 39375537, 2024).
Insulin resistance (2 papers, 2018 to 2022). Increased resistance towards insulin, that is, diminished effectiveness of insulin in reducing blood glucose levels. "Therefore, it is expected that further developments in the field will be able to overrule or demonstrate the importance of TRPC5 complexes in insulin resistance and/or their roles as sensors of glucose levels." (PMID 35455971, 2022). "Long-term exposure to a “Westernized” HFD causes sexually differentiated insulin resistance that, among other things, is associated with a reduced insulin receptor-mediated activation of TRPC5 channels in POMC neurons from male but not female guinea pigs." (PMID 29973869, 2018). "As shown presently and reported recently, insulin purified from guinea pig and other animal sources also depolarizes POMC neurons via a PI3K-induced activation of TRPC5 channels, and these neurons are a critical substrate in the development of sexually differentiated diet-induced insulin resistance." (PMID 29973869, 2018). "There is little data on the pancreatic expression of TRPC5 and no reports so far on the role of this receptor in insulin resistance." (PMID 35455971, 2022).
Intellectual disability (2 papers, 2022 to 2024). "In addition, three de novo variants in TRPC5 (p.(Pro667Thr), p.(Arg71Gln), p.(Trp225*)) had been identified in patients with intellectual disability and/or autism disorders in the literature." (PMID 36323681, 2022). "Finally, we report damaging variants in CDK16 and TRPC5 in patients with intellectual disability or autism spectrum disorders." (PMID 36323681, 2022).
ischemia (2 papers, 2020). A hypoperfusion of the BLOOD through an organ or tissue caused by a PATHOLOGIC CONSTRICTION or obstruction of its BLOOD VESSELS, or an absence of BLOOD CIRCULATION. "Additionally, using a mouse model of ischemia-reperfusion injury, we found that TRPC5 KO mice had fewer neurons undergoing PS exposure and apoptosis, suggesting a protective effect of TRPC5 inhibition." (PMID 32110987, 2020). "While the examination of cerebral slices of animals subject to ischemia/reperfusion revealed reduced PS externalization and apoptosis in TRPC5 knockout mice, whether these translate into protection against cerebral infarction and/or behavioral neurological impairments remains to be elucidated." (PMID 33490083, 2020). "Collectively, the present study suggested that TRPC5-PLSCR1 is a signaling complex mediating PS externalization and apoptosis in neurons and that TRPC5 plays a pathological role in cerebral-ischemia reperfusion injury." (PMID 32110987, 2020). "In our results, compared with wild-type mice, TRPC5 KO mice showed substantially less PS externalization and less apoptosis of cerebral neurons, suggesting that TRPC5 KO mice experienced less injury following ischemia-reperfusion and might have a better prognosis." (PMID 32110987, 2020). "Given that TRPC1 and TRPC6 may play some neuroprotective function during ischemia/reperfusion, it is plausible that the detrimental actions are mainly mediated by TRPC4 and/or TRPC5, and these two TRPC isoforms may dominate the cortical neuronal responses to ischemic insults." (PMID 33490083, 2020).
liver disease (2 papers, 2017 to 2020). "Endogenous modulators of TRPC5 include a range of phospholipids that have an established role in liver disease, including lysophosphatidylcholine (LPC)." (PMID 28539583, 2017). "This was associated with a decrease of hepatic acid bile and lipid content in the TRPC5 KO mice, indicating that TRPC5 may be an important target for liver disease therapies." (PMID 32872338, 2020). "Modulation of TRPC5 activity may present as a novel therapeutic target for liver disease." (PMID 28539583, 2017).
migraine (2 papers, 2021 to 2023). "The activation and role of amygdaloid TRPC4/TRPC5 in migraine should be further explored in future studies." (PMID 34790097, 2021).
nasal polyps (2 papers, 2021 to 2022). "Expression of TRPC5 in nasal polyps was positively correlated with the number of eosinophils, IL-6 expression and inflammation, suggesting that these pathways may respond differently to different inflammatory responses." (PMID 34836549, 2021).
nephrotic syndrome (2 papers, 2016 to 2018). A collection of symptoms that include severe edema, proteinuria, and hypoalbuminemia; it is indicative of renal dysfunction. "TRPC5 is expressed in podocytes and has been suggested to play a role in nephrotic syndromes and can be mobilized to surface under in vitro conditions designed to mimic severe primary FSGS." (PMID 29785489, 2018). "The identification of the two Ca2+ permeant channels TRPC5 and TRPC6 as mediators of this pathway not only bolstered the importance of podocyte cytoskeleton dynamics but also revealed promising drug targets for treatment-resistant nephrotic syndrome." (PMID 26490951, 2016).
neuropathic pain (2 papers, 2022 to 2026). Chronic pain caused by damage to nerve fibers. "Additionally, TRPC5 expression is required for the development of mechanical allodynia in several inflammatory and neuropathic pain models, although the contribution of epidermal TRPC5 to injury induced mechanical hypersensitivity remains to be explored." (PMID 36053009, 2022). "Finally, we investigated whether TRPC5 activation could enhance the analgesic effect of morphine in a neuropathic pain model." (PMID 41111460, 2026).
postpartum depression (2 papers, 2024). A type of clinical depression that occurs after childbirth. "Strikingly, the Trpc5K34del mutation causes depressive behavior only in mouse dams but not in virgin females or males, highlighting a specific role for TRPC5 in the pathophysiology of postpartum depression." (PMID 38959890, 2024). "Women carrying TRPC5 deletions had severe postpartum depression." (PMID 38959890, 2024).
renal carcinoma (2 papers, 2018 to 2022). A carcinoma arising from the epithelium of the renal parenchyma or the renal pelvis. "The roles of TRPC4 and TRPC5 in migration/proliferation of cancer cells, angiogenesis, cancer cell multi-drug resistance and (−)EA-induced renal cancer cell death have been reviewed in 2016." (PMID 29865154, 2018). "Indeed, in our experiments, AC1903 inhibited multiple TRPC channels including TRPC3, TRPC4, TRPC5, TRPC6, TRPC4–C1, and TRPC5–C1, as well as endogenous TRPC1:C4 channels in A498 renal cancer cells, all with low micromolar IC50 values (1.8–18 μM)." (PMID 34999117, 2022).
Adrenal insufficiency (1 paper, 2024). Insufficient production of steroid hormones (primarily cortisol) by the adrenal glands. "The similarities in sympatho-adrenal insufficiency between Trpc5 KO mice and HAAF patients identified for the first time, represent a new avenue for the development of new TRPC5-associated diagnostic and treatment options for the long-term diabetic complication HAAF." (PMID 39375537, 2024).
adrenocortical tumors (1 paper, 2025). "TRPC5 is highly expressed in adrenal chromaffin cells and modulates Ca2+-dependent catecholamine release, a pathway frequently altered in adrenocortical tumors." (PMID 41470046, 2025).
Anorexia (1 paper, 2018). Lack of desire to eat (loss of appetite). "In contrast, deletion of Trpc5 in all POMC neurons leads to an age-dependent increase in body weight, with increased food intake, decreased energy expenditure, and attenuated leptin-mediated anorexia, although glucose homeostasis was unchanged." (PMID 30304668, 2018).
basal cell carcinoma (1 paper, 2025). A carcinoma involving the basal cells. "This makes the research on TRPC5 a further new diagnostic and histological instrument to differentiate between basal cell carcinoma and squamous cell carcinoma." (PMID 40723382, 2025). "This study is the first to examine TRPC5 expression profiles in common skin cancers, including basal cell carcinoma (BCC), squamous cell carcinoma (SCC), malignant melanoma (MM), and nevus cell nevi (NCN)." (PMID 40723382, 2025). "A key result of our study was that TRPC5 expression was less frequent in basal cell carcinoma (BCC) than in squamous cell carcinoma (SCC)." (PMID 40723382, 2025). "Our findings revealed a notably lower expression of TRPC5 in basal cell carcinoma (BCC) in comparison to squamous cell carcinoma (SCC), with nearly half of the BCC cases showing no expression at all." (PMID 40723382, 2025). "Here, we examine for the first time the TRPC5 expression profiles in skin tumors, i.e., basal cell carcinoma (BCC), squamous cell carcinoma (SCC), malignant melanoma (MM), and nevus cell nevi (NCN)." (PMID 40723382, 2025).
Cerebral ischemia (1 paper, 2020). Restriction of arterial blood supply to the brain associated with insufficient oxygenation to support the metabolic requirements of the tissue. "The two main findings of the present study are that TRPC5 physically associates with PLSCR1 to facilitate PS externalization in HEK293 cells and mouse cerebral neurons, and that inhibiting TRPC5 may have a protective effect in cerebral ischemia-reperfusion injury." (PMID 32110987, 2020).
endocarditis (1 paper, 2022). Inflammation of the endocardium. "Meanwhile, TRPC5 is involved in inflammatory pain in various disease models; hence, this channel may contribute to cardiac inflammatory pain such as in endocarditis, myocarditis, and pericarditis, instead of contributing to ischaemic pain." (PMID 35269964, 2022).
epidermolysis bullosa (1 paper, 2022). Epidermolysis bullosa (EB) is a group of genetic skin diseases that cause the skin to blister very easily. "Indeed, a recently reported selective TRPC5 inhibitor, AC1903, consistently suppressed G418 uptake and G418-induced PTC readthrough in the DMS-114 cancer cell line and junctional epidermolysis bullosa (JEB) patient-derived keratinocytes." (PMID 34999117, 2022).
Focal cortical dysplasia (1 paper, 2019). A type of malformation of cortical development that primarily affects areas of neocortex. "In cortical lesions of the focal cortical dysplasia, common intractable epilepsy in both pediatric and adult patients, the expression of TRPC5 is significantly increased in glutamatergic and GABAergic neurons." (PMID 30062674, 2019).
Hypercalciuria (1 paper, 2025). "The TRPC5 and TRPC6 (transient receptor potential) channels play a key role in the renal reabsorption of calcium; mice lacking these proteins suffer from hypercalciuria and bone disease." (PMID 40218942, 2025).
hypertensive nephropathy (1 paper, 2021). Kidney damage that results from chronically elevated blood pressure; complications include glomerular damage resulting in proteinuria and hematuria. "Our previous studies have demonstrated that activation of TRPC5 channels induces Rac1 activity in podocytes, which leads to the ROS production, cytoskeletal remodeling and podocyte loss in the angiotensin II type 1 receptor transgenic and spontaneous hypertensive nephropathy rat models." (PMID 34621762, 2021).
joint disease (1 paper, 2017). "We hypothesised that global deletion or pharmacological antagonism of TRPC5 would exacerbate joint disease associated with increased inflammation and pain." (PMID 27165180, 2017). "We corroborated these results by measuring cytokine concentrations in synovial lavage fluid and in plasma samples and show that TRPC5 deletion or antagonism increased the local secretion of a number of critical pro-inflammatory cytokines (eg, TNFα, IL-1β) with an established role in joint disease." (PMID 27165180, 2017).
kidney failure (1 paper, 2022). An acute or chronic condition that is characterized by the inability of the kidneys to adequately filter the blood. "Furthermore, inhibiting the TRP channels related genes TRPC5 could protect podocytes in the kidney and prevent kidney failure, TRP channels may be a new target for the prevention and treatment of IgAN and IBD in the future." (PMID 35769467, 2022).
kidney injuries (1 paper, 2025). "Furthermore, GQDs targeted TRPC5 over CCB, underscoring their potential as a novel nanomedicine addressing TRPC5 overexpression, a key contributor to podocyte‐related kidney injuries." (PMID 39739624, 2025).
lung carcinoma (1 paper, 2013). "The mRNAs for TRPC5 and TRPC7 were undetectable in normal and lung cancer tissues." (PMID 23840757, 2013).
lupus (1 paper, 2023). "Nevertheless, it was previously shown that the membrane incorporation of TRPC5 requires activated Rac139–41, which was in turn down-regulated by MMF in a murine lupus model." (PMID 37644089, 2023).
malignant glioma (1 paper, 2021). A grade III or grade IV glioma arising from the central nervous system. "As emphasized above for TRPM8, there is still a long road before these types of compounds targeting TRPC5 will enter clinics to treat malignant glioma patients." (PMID 34458247, 2021).
malignant melanoma (1 paper, 2025). "Additionally, TRPC5 expression in BCC was significantly lower compared to the epidermal portions of malignant melanoma (MM) and nodular compound nevi (NCNs)." (PMID 40723382, 2025).
multiple myeloma (1 paper, 2022). "The mechanism of action of this novel class of molecules includes the induction of cell death via calcium overload, a finding that was dependent on TRPC1/TRPC4/TRPC5 expression in multiple myeloma cell lines." (PMID 35804837, 2022).